GCG (glucagon)
Diseases named in the same sentence as GCG in open-access papers (continued):
Sharing a sentence is not in itself a finding about the gene and the disease.
myopia (14 papers, 2007 to 2025). "Several studies have identified an association between metabolic control of glucose (insulin/glucagon pathways) and myopia in humans." (PMID 35262731, 2022). "Future studies exploring the effect of common variants annotated to GJD2(Cx36) on insulin/glucagon levels and the subsequent potential impact on myopia development may help to elucidate this potential mechanism." (PMID 35262731, 2022). "–202 Interestingly, insulin and glucagon show opposing effects on eye growth in chickens, with glucagon mostly increasing choroidal thickness (associated with myopia inhibition) and insulin mostly increasing ocular elongation, proposed to be controlled by glucagon-positive amacrine cells." (PMID 35262731, 2022). "Research indicates that glucagon acts as an inhibitory signal for eye elongation, with higher glucagon levels or receptor activation potentially counteracting the progression of myopia." (PMID 40933557, 2025). "As our knowledge of the pathophysiology of myopia has grown, a number of retinal signaling factors such as dopamine, acetylcholine, retinoic acid, nitric oxide and glucagon have been identified as potential contributors to the development of myopia." (PMID 40141806, 2025). "Experimental studies using animal models have demonstrated that increasing glucagon levels or enhancing glucagon receptor signaling can reduce myopia progression." (PMID 40933557, 2025). "These cross-species mechanistic insights support further exploration of glucagon-based therapies for myopia." (PMID 40933557, 2025). "The most significantly altered pathways identified in this analysis implicate early cone phototransduction, mitochondrial bioenergetics, retinol metabolism, complement and glucagon in early recovery from FD and in the myopia pathophysiology." (PMID 33674625, 2021). "It has also been demonstrated that glucagon agonists can prevent experimentally induced myopia, while glucagon antagonists can prevent compensation for positive-lens wear, suggesting a role for glucagon in the modulation of eye growth." (PMID 20405027, 2010). "The activation of glucagon signaling was demonstrated to inhibit experimental myopia in chicks." (PMID 39876870, 2024). "The ability of glucagon agonists to block experimental myopia is consistent with such a pathway." (PMID 20405027, 2010). "Although Pax6 also transactivates the glucagon promoter, which is a “stop” for myopia, insulin might overcome the effects of glucagon in the development of myopia." (PMID 19907666, 2009). "Down-regulation of gene expression for the precursor of a peptide hormone/transmitter such as glucagon is most likely indicative of a reduced rate of synthesis of the peptide precursor, and of a decreased rate of glucagon release during the development of experimental myopia." (PMID 20405027, 2010). "A potential connection between Egr-1 and myopia was first described in the chick, where it was found that the expression of ZENK correlates with the sign of defocus imposed by lenses in a subset of amacrine cells (AC), specifically the glucagon AC." (PMID 17653032, 2007).
neuroendocrine tumors (14 papers, 2010 to 2025). "Glucagonomas, neuroendocrine tumors originating from the pancreas marked by excessive glucagon secretion, present a diagnostic challenge due to their rarity and diverse symptomatology." (PMID 38021839, 2023). "Characterization of the PNEN confirmed it was a neuroendocrine neoplasm as it immuno-stained positively for chromogranin and glucagon." (PMID 33150274, 2020). "A periampullary mass biopsy proved to be a neuroendocrine tumor, with positive immunohistochemical reactivity to DakoCytomation's Polyclonal Rabbit Anti-Human Glucagon." (PMID 20550685, 2010). "Only in a few cases of pancreatic (likely glucagon-producing) neuroendocrine tumours with exceptionally high expression GPR68 may be of some interest in this respect." (PMID 31652823, 2019). "In the present study, the results of the microscopic examination were consistent with the features of a neuroendocrine neoplasm, and the immunohistochemical staining was positive for glucagon, synaptophysin and chromogranin A. These findings confirmed the diagnosis of a glucagonoma." (PMID 25789004, 2015). "Although hormonal testing did not reveal a clear cause, we suspect that glucagon secretion from a neuroendocrine tumor may have contributed to the higher preoperative insulin requirement." (PMID 40135013, 2025).
Stroke (14 papers, 2019 to 2026). Sudden impairment of blood flow to a part of the brain due to occlusion or rupture of an artery to the brain. "In addition, the prevalence of stroke increased with ascending quartiles of glucagon levels in female patients (P = 0.023)." (PMID 41648993, 2026). "Low HbA1c represents that the blood glucose level before stroke is at a low level for a long time, which transfers the blood glucose threshold of adrenaline to a low plasma glucose level, reducing the response level of elevated blood glucose and slowing the response of glucagon." (PMID 33935947, 2021).
diabetic cardiomyopathy (13 papers, 2013 to 2025). Diabetic cardiomyopathy is a disorder of the heart muscle in people with diabetes. "Our data is supported by previous studies showing that glucagon antagonism mitigates diabetic cardiomyopathy in Leprdb/db diabetic mice, coinciding with improved whole body insulin signalling." (PMID 30626440, 2019). "However, seven signaling pathways - Wnt, HIF1, TGF beta, IL17, mTOR, glucagon, and VEGF - along with pathways involved in diabetic cardiomyopathy and necroptosis, were exclusively enriched in the SITA group." (PMID 41282288, 2025). "KEGG enrichment analyses showed that TCA cycle, pyruvate metabolism, glycolysis/gluconeogenesis, central carbon metabolism in cancer, carbon metabolism, glucagon signaling pathway, HIF-1 signaling pathway, biosynthesis of cofactors, and diabetic cardiomyopathy were mostly enriched." (PMID 36440046, 2022).
Anxiety (12 papers, 2017 to 2025). Intense feelings of nervousness, tension, or panic often arise in response to interpersonal stresses. "Several measures were obtained during both conditions (plasma, insulin, glucagon, cortisol levels, testosterone and luteinizing hormone levels; skin conductance, heart rate and anxiety and desire to drink)." (PMID 36235578, 2022).
coronary artery disease (12 papers, 2015 to 2026). "From a clinical practice perspective, our findings suggest that for female T2DM patients, fasting glucagon levels might have the potential to serve as an auxiliary biomarker to help identify individuals at higher risk for coronary heart disease." (PMID 41458542, 2025). "Mendelian randomization studies in the general population suggest that genetically determined higher glucagon levels may be a potential risk factor for ischemic heart disease." (PMID 41458542, 2025).
liver fibrosis (12 papers, 2021 to 2025). "Survodutide (BI 456906) is a dual agonist of glucagon (GCG) and GLP-1 receptor that can inhibit the activation of HSCs and inflammation to mitigate liver fibrosis." (PMID 40492139, 2025). "Regarding drug-induced effects on liver fibrosis, Dr. Judith Ertle presented the positive outcomes of a GLP-1/glucagon dual agonist, survodutide, which acts mainly through a weight-dependent mechanism of action." (PMID 40142664, 2025).
asthma (11 papers, 2018 to 2025). "Prior investigations demonstrate that glucagon causes bronchial relaxation in patients with asthma, including those suffering from refractory asthma exacerbation." (PMID 31019244, 2019). "Two confirmatory testing panels were used—the primary panel was betaxolol-glucagon (children ≥15 kg) or glucagon (<15 kg or asthma), and the secondary was arginine-insulin (children ≥15 kg) or arginine (children <15 kg)." (PMID 33324312, 2020). "Since the TCD4+ cells are the major T cells involved in the pathogenesis of asthma, and as we observed that glucagon inhibited activation of T lymphocytes in vitro, we investigated the direct action of glucagon on TCD4+ cells." (PMID 31019244, 2019). "Since all these inflammatory cells express GcgR, our data indicate that those seem to be crucial cell targets in asthma pathophysiology which are modulable by glucagon." (PMID 31019244, 2019). "Due to the importance of T lymphocytes in the pathophysiology of asthma, we evaluated the effect of glucagon upon accumulation of Tαβ lymphocytes in BAL, mediastinal lymph nodes and the lungs of mice challenged with OVA." (PMID 31019244, 2019). "The purpose of this study was to evaluate the effectiveness of intranasal glucagon on the development of the airway inflammation and tissue remodeling in a murine model of asthma." (PMID 31019244, 2019). "For examples, antibody mAb7 inhibits the glucagon GCGR receptor through a unique allosteric mechanism; and an allosteric anti-tryptase antibody can treat mast cell-mediated severe asthma." (PMID 34887850, 2021). "Here, we investigate if glucagon would prevent airway hyperreactivity (AHR), lung inflammation, and remodeling in a murine model of asthma." (PMID 31019244, 2019).
breast carcinoma (10 papers, 2013 to 2025). "However, higher GCG expression is associated with decreased survival in breast cancer, cervical squamous cell carcinoma, esophageal adenocarcinoma, head-neck squamous cell carcinoma, ovarian cancer, stomach adenocarcinoma, and uterine corpus endometrial carcinoma." (PMID 39777709, 2025). "Other notable pathways were glucagon signaling, a tight junction, and multiple cancer-related pathways such as hepatocellular carcinoma, olorectal cancer, and breast cancer." (PMID 40806181, 2025). "Along with the detrimental effects on muscle function, we observed a rise in gastrointestinal incretins (GIP and GLP-1), C-peptide, and glucagon levels, along with low PAI-1 levels, in breast cancer patients, independently." (PMID 38397883, 2024).
COVID-19 (10 papers, 2021 to 2024). A disease caused by infection with severe acute respiratory syndrome coronavirus 2. "Acute COVID-19 children exhibited elevated levels of C-peptide, Insulin and Glucagon in comparison to convalescent and control children." (PMID 37013538, 2023). "We measured the pancreatic hormone levels (C-peptide, Insulin and Glucagon) in acute, convalescent COVID-19 and control children." (PMID 37013538, 2023). "Acute COVID-19 children had significantly elevated levels of adipsin, leptin, insulin, C-peptide, glucagon and ghrelin in comparison to convalescent COVID-19 and controls." (PMID 37013538, 2023). "Similarly, convalescent COVID-19 children had elevated levels of adipsin, leptin, insulin, C-peptide, glucagon, ghrelin and Glucagon-like peptide-1 (GLP-1) in comparison to control children." (PMID 37013538, 2023). "Similarly, convalescent COVID-19 children also exhibited elevated levels of C-peptide, Insulin and Glucagon in comparison to control children." (PMID 37013538, 2023). "By double immunohistochemical staining of insulin (AP-red) and glucagon (DAB-brown), the lesions in the islets of the elder COVID-19 models were clearly shown." (PMID 38609366, 2024). "Of note, glucagon mRNA levels were not altered in virus-positive nor in virus-negative COVID-19 cases compared to controls, thus suggesting normal alpha cell functioning." (PMID 37246981, 2023). "Conversely, hypoglycemia may develop in SARS-CoV due to hepatic and pancreatic alpha cell injury, despite the fact that alpha cell dysfunction and lower glucagon serum levels were not confirmed in COVID-19 patients." (PMID 34124187, 2021).
Crohn disease (10 papers, 2009 to 2024). A gastrointestinal disorder characterized by chronic inflammation involving all layers of the intestinal wall, noncaseating granulomas affecting the intestinal wall and regional lymph nodes, and transmural fibrosis. "Further experiments are needed to assess the role of catecholamines and their metabolites, cortisol and glucagon in glucose metabolism in Crohn disease." (PMID 34535873, 2021). "Additionally, we detected a trend for a positive correlation, thought it was not significant, between the expression of GCG and ACE2 mRNAs both in human samples of Crohn’s disease patients and DSS mice." (PMID 35406751, 2022).
hepatocellular carcinoma (10 papers, 2018 to 2026). A malignant tumor that arises from hepatocytes. "Other hormones that may cause paraneoplastic diarrhea include glucagon (glucagonoma), gastrin (gastrinoma or hepatocellular carcinoma), somatostatin (somatostatinoma or pheochromocytoma), and the prostaglandins (hepatocellular carcinoma)." (PMID 29177551, 2018). "We determined the effects of experimental cholesterol depletion and loading on glucagon-mediated cAMP production, ligand internalisation and glucose production in human hepatoma cells, mouse and human hepatocytes." (PMID 35718339, 2022). "Given the physiological relevance of hepatocytes for GCG signalling and the cell line dependence of RAMP activity, we next examined this phenomenon in Huh7 hepatoma cells, which express low levels of endogenous RAMP2." (PMID 34271220, 2021).
hypertriglyceridemia (10 papers, 2018 to 2025). A laboratory test result indicating elevated triglyceride concentration in the blood. "In hypertriglyceridemia, free fatty acids lead to high glucagon secretion and increase TG accumulation and free fatty acids in pancreatic α cells." (PMID 34457002, 2021). "If present, this could in part explain the known side effect of hypertriglyceridemia seen in horses treated with SGLT2i, as increased glucagon secretion leads to gluconeogenesis, glycogenolysis and lipolysis." (PMID 41408266, 2025). "Also, hypertriglyceridemia and increased blood fatty acid levels reduce glucagon release in rats, dogs and guinea pigs." (PMID 34115756, 2021). "Furthermore, hypertriglyceridemia augments the hyperglycemic effects of glucagon." (PMID 36904293, 2023). "However, hypertriglyceridemia observed during lactation may be related to hormonal regulation (P4, glucocorticosteroids, catecholamines, and glucagon) and NEFA level increase used for TG synthesis." (PMID 34840462, 2021).
migraine (10 papers, 2017 to 2026). "Since the balance of glucagon/catecholamines and insulin controls lipolysis, insulin resistance is suggested to be associated with migraine pathophysiology may also account for the higher levels of UFAs in CM plasma." (PMID 34531722, 2021). "In a study examining the effects of insulin, glucagon, and leptin in a rat model of migraine, changes in the transmission of trigeminal nociceptive inputs were identified, which provides insight into the dysregulated glucose state associated with migraines." (PMID 36248663, 2022). "Peptides such as insulin, glucagon, and leptin, which are involved in blood glucose and appetite regulation, could influence the neurobiology of migraines." (PMID 39452037, 2024). "Besides its role in migraines, animal studies revealed an association between CGRP and the modulation of insulin and glucagon production." (PMID 35627115, 2022). "The KH patient with a heterozygous NEK11 mutation had recurrent migraine, cognitive and motor deficits, mild liver affection, absent glucose response to i.m. glucagon and decreased p-IGFBP3 as additional features." (PMID 33849624, 2021). "A study on male rats observed that insulin and glucagon can alter the transmission of nociceptive inputs in the trigeminal–cervical complex suggesting another important potential neurobiological link between migraine and impaired metabolic homeostasis." (PMID 32481555, 2020). "It has been suggested that insulin, glucagon, and leptin may alter the transmission of nociceptive inputs from the trigeminal nerve to higher brain regions, implying that adipokine signaling could influence specific neural networks involved in the development of migraines." (PMID 39452037, 2024). "Finally, in light of the proposed inhibitory role for 5-HT1F in glucagon secretion, the 5-HT1F receptor agonist, Lasmiditan, which is currently in Phase III clinical trials for migraines, could be a potential therapeutic target to suppress glucagon release in diabetics." (PMID 28979187, 2017).